NUDT16 (nudix hydrolase 16)
Description:
RNA-binding and decapping enzyme that catalyzes the cleavage of the cap structure of snoRNAs and mRNAs in a metal-dependent manner. Part of the U8 snoRNP complex that is required for the accumulation of mature 5.8S and 28S rRNA. Has diphosphatase activity and removes m7G and/or m227G caps from U8 snoRNA and leaves a 5'monophosphate on the RNA. Also catalyzes the cleavage of the cap structure on mRNAs. Does not hydrolyze cap analog structures like 7-methylguanosine nucleoside triphosphate (m7GpppG). Also hydrolysis m7G- and m227G U3-capped RNAs but with less efficiencies. Has broad substrate specificity with manganese or cobalt as cofactor and can act on various RNA species. Binds to the U8 snoRNA; metal is not required for RNA-binding. May play a role in the regulation of snoRNAs and mRNAs degradation. Also acts as a phosphatase; hydrolyzes the non-canonical purine nucleotides inosine diphosphate (IDP) and deoxyinosine diphosphate (dITP) as well as guanosine diphosphate (GDP), deoxyguanosine diphosphate (dGDP), xanthine diphosphate (XDP), inosine triphosphate (ITP) and deoxyinosine triphosphate (ITP) to their respective monophosphate derivatives and does not distinguish between the deoxy- and ribose forms. The order of activity with different substrates is IDP > dIDP >> GDP = dGDP > XDP = ITP = dITP. Binds strongly to GTP, ITP and XTP. Participates in the hydrolysis of dIDP/IDP and probably excludes non-canonical purines from RNA and DNA precursor pools, thus preventing their incorporation into RNA and DNA and avoiding chromosomal lesions. Exhibits decapping activity towards NAD-capped RNAs and FAD-capped RNAs. Exhibits decapping activity towards dpCoA-capped RNAs in vitro (By similarity).
Synonyms: FLJ31265
Tractability: Small molecule: a structure with a bound ligand is known; it has a binding pocket of medium quality. PROTAC: ubiquitination databases record sites on it; its protein half-life has been measured.
Gene: Protein-coding gene on chromosome 3 (131,381,671 to 131,388,830, forward strand). Ensembl gene ENSG00000198585.
Subcellular location: Nucleus; Nucleus, nucleoplasm; Nucleus, nucleolus; Cytoplasm
Subcellular location (Human Protein Atlas): Nucleoli; Nucleoplasm
Pathways (Reactome):
Metabolism: Phosphate bond hydrolysis by NUDT proteins
Gene Ontology:
Molecular function: 5'-(N(7)-methylguanosine 5'-triphospho)-[mRNA] hydrolase activity; chloride ion binding; cobalt ion binding; dIDP phosphatase activity; identical protein binding; IDP phosphatase activity; magnesium ion binding; manganese ion binding; metalloexopeptidase activity; mRNA binding; phosphodiesterase decapping endonuclease activity; protein homodimerization activity; RNA NAD-cap (NMN-forming) hydrolase activity; snoRNA binding; dITP diphosphatase activity; nucleoside diphosphate phosphatase activity
Biological process: mRNA catabolic process; NAD-cap decapping; positive regulation of cell cycle process; sno(s)RNA catabolic process; dITP catabolic process; negative regulation of rRNA processing
Cellular component: cytoplasm; nucleolus; nucleoplasm; nucleus
Genetic constraint (gnomAD): Loss-of-function variants: 12 observed, 12.09 expected, observed/expected ratio (o/e) 0.99, 90% interval 0.63 to 1.59. The upper end of that interval is the gene's LOEUF score, 1.59, which puts it in group 6 of 6, group 1 being the genes least tolerant of losing a copy. Missense variants: 303 observed, 277.75 expected, observed/expected ratio (o/e) 1.09, 90% interval 0.99 to 1.2. Synonymous variants: 129 observed, 122.86 expected, observed/expected ratio (o/e) 1.05, 90% interval 0.91 to 1.22.
Homologues: Orthologues: pig NUDT16 (83% identical), dog NUDT16 (80% identical), mouse Nudt16 (79% identical), rat Nudt16 (77% identical), mouse Nudt16l2 (69% identical), rat Nudt16l2 (59% identical), tropical clawed frog nudt16 (59% identical), zebrafish zgc:103759 (47% identical). Paralogues in human: NUDT16L1 (55% identical).
Diseases named in the same sentence as NUDT16 in open-access papers:
NUDT16 is named in the same sentence as 21 diseases in open-access papers, as found by Europe PMC text mining. Sharing a sentence is not in itself a finding about the gene and the disease. The quoted sentences say what the papers report.
breast carcinoma (3 papers, 2023 to 2025). "The results showed that 17 m7GRGs were risk factors and significantly impacted breast cancer prognosis, whereas NUDT10, NUDT3, EIF4E3, SNUPN, NUDT16, IFIT5 and EIF3D were favourable prognostic factors." (PMID 37353728, 2023). "NUDT1, NUDT2, NUDT5, and NUDT16 were overexpressed in breast cancer tissue." (PMID 40839607, 2025). "Therefore, we sought to investigate whether NUDT16-mediated dePARylation of SETD3 contributes to the regulation of replication stress resolution and radioresistance in breast cancer cells, and a comet assay was performed." (PMID 38272222, 2024).
hepatocellular carcinoma (2 papers, 2022 to 2025). A malignant tumor that arises from hepatocytes. "Given the potential role of NUDT16 in hepatocellular carcinoma progression, our previous study comparing the expression of NUDT16 in tumor and normal tissues showed that NUDT16 was highly expressed in tumor tissues." (PMID 36389726, 2022).
liver cancer (2 papers, 2019 to 2023). An epithelial or non-epithelial malignant neoplasm that arises from the liver. "Among the genes associated with the prognosis of liver cancer, the genes associated with shorter survival period are AGO2, DCPS, IFIT5, LARP1, NCBP2, NUDT10, and NUDT16; the genes associated with longevity are EIF4E3, EIF4G3, METTL1, NCBP1, NSUN2, NUDT11, NUDT4, and WDR4." (PMID 36845384, 2023). "A (deoxy)insoine diphosphatase, NUDT16 (spearman = − 0.324, p < 0.005) was identified for the MSL, which shows that this protein has a biomarker-related role in RTK inhibitor treatment on liver cancer cell lines." (PMID 31208363, 2019).
acute myeloid leukaemia (1 paper, 2017). "In acute myeloid leukaemia (AML), promoter hypermethylation of NUDT16, an RNA decapping enzyme, triggers an increase in c-myc half-life mRNA, contributing to its activation." (PMID 28931650, 2017).
colorectal cancer (1 paper, 2016). A primary or metastatic malignant neoplasm that affects the colon or rectum. "The level of NUDT16 protein in WI38 cells was also similar to that in HeLa MR cells and higher than that in human colorectal cancer cell lines." (PMID 27618981, 2016).
cyst (1 paper, 2025). A sac-like closed membranous structure that may be empty or contain fluid or amorphous material. "To explore potential roles of Subclade II NUDTs in plant‐pathogen interactions, we first examined transcript abundance of NUDT12, NUDT13, and NUDT16 during Arabidopsis infection by cyst nematodes (CN) using previously published transcriptomic data." (PMID 41165244, 2025).
Huntington disease (1 paper, 2025). Huntington disease (HD) is a rare neurodegenerative disorder of the central nervous system characterized by unwanted choreatic movements, behavioral and psychiatric disturbances and dementia. "Studies have shown that NUDT16 plays a certain role in DNA damage-related diseases, such as polyglutamine (polyQ) diseases, including Huntington’s disease (HD)." (PMID 40895564, 2025).
ovarian carcinoma (1 paper, 2025). A malignant neoplasm originating from the surface ovarian epithelium. "We also found that high expression of NUDT16 in ovarian cancer tissue is associated with improved patient prognosis." (PMID 40895564, 2025). "The risk score constructed based on DCP2 and NUDT16 is an independent prognostic factor for ovarian cancer, suggesting the important functions of these two genes in ovarian cancer, which undoubtedly deserves further study." (PMID 40895564, 2025). "Further analysis showed that two m7g regulator genes, DCP2 and NUDT16, could be used to construct a prognostic risk model of ovarian cancer, and that risk scores were significantly associated with ovarian cancer prognosis." (PMID 40895564, 2025). "Furthermore, we investigated the function of NUDT16 and its association with ovarian cancer prognosis." (PMID 40895564, 2025). "These suggest that high expression of NUDT16 may be a protective factor for ovarian cancer." (PMID 40895564, 2025). "The flat panel cloning method visually shows that the number of clonogenic cells from ovarian cancer cells knocked down by DCP2 is smaller than that of the control group, while the clonogenic ability of cells knocked down by NUDT16 is diminished." (PMID 40895564, 2025). "m7G modification affects the cellular composition of the immune microenvironment in ovarian cancer, and two key m7G modification-regulated genes, DCP2 and NUDT16, promotes the proliferation and metastases of ovarian cancer cells, and its high expression is associated with poor prognosis." (PMID 40895564, 2025).
psoriasis (1 paper, 2021). An autoimmune condition characterized by red, well-delineated plaques with silvery scales that are usually on the extensor surfaces and scalp. "Furthermore, genes encoding other PAR hydrolases were specifically up-regulated in psoriasis lesional skin (ARH3) or down-regulated (NUDT16 and ENPP1)." (PMID 34748530, 2021).
Sepsis (1 paper, 2022). Sepsis is defined as life-threatening organ dysfunction caused by a dysregulated host response to infection. "The robustness of the increase in NUDT16 transcript abundance in the context of sepsis can be further assessed in a range of settings and methodologies." (PMID 35174610, 2022). "We employed systematic literature mining, reductionist approach to gene expression profile and empirical in vitro work to highlight the role of a Nudix hydrolase family member, NUDT16, in sepsis." (PMID 35174610, 2022). "To summarize the current knowledge about NUDT16 in the context of sepsis, we conducted a PubMed query that comprised of its official symbol, name and known aliases." (PMID 35174610, 2022). "The role of NUDT16 in the context of sepsis or inflammation exhibits a knowledge gap and should be further explored experimentally." (PMID 35174610, 2022). "Furthermore, the abundance of literature linking ADP ribosylation and inflammation provides additional avenues to explore how NUDT16 affects or is affected during the progression of an infection towards sepsis." (PMID 35174610, 2022). "Indeed, we explored the expression pattern of NUDT16 during sepsis in seven additional public datasets (see detailed step in Materials and Methods) composed of different tissue matrixes and cohorts." (PMID 35174610, 2022). "However, we showed that a joint interpretation of available literature and transcript profiling data conducted herein, along with basic experimental data, permitted inferences as to what role NUDT16 may play during inflammation and sepsis." (PMID 35174610, 2022). "The results indicate that there is no known role for NUDT16 in the context of sepsis, inflammation or neutrophil immunobiology in the current published literature." (PMID 35174610, 2022). "We provided support for an indirect link between NUDT16 and inflammatory processes through ADP‐ribosylation and RNA decapping activities and infer the potential role for NUDT16 in the degradation of mRNAs and/or post‐translational regulation of inflammatory molecules during sepsis." (PMID 35174610, 2022). "However, we found no overlaps between NUDT16 literature with sepsis, inflammation or neutrophils." (PMID 35174610, 2022).
T-cell acute lymphoblastic leukemia (1 paper, 2022). Acute lymphoblastic leukemia of T-cell origin. "A previous study reported that in T cell acute lymphoblastic leukemia, the epigenetic loss of NUDT16 mediated the activation of C-MYC and promoted tumor progression." (PMID 36226166, 2022).
thyroid cancer (1 paper, 2021). "We found six RBPs (AZGP1, IGF2BP2, MEX3A, NUDT16, NUP153, USB1) independently associated with prognosis of patients with thyroid cancer according to univariate and multivariate Cox proportional hazards regression models." (PMID 33816259, 2021).
cancer (9 papers, 2015 to 2025). A tumor composed of atypical neoplastic, often pleomorphic cells that invade other tissues. "The bioinformatics analysis further supports that a greater understanding of the underlying DNA repair pathways for NUDT16 may have a significant impact on the development of cancer." (PMID 38324469, 2024). "We analyzed TCGA data and found that NUDT16 was expressed at lower levels in most pan-cancer tissues compared to normal tissues." (PMID 38324469, 2024). "Importantly, depletion of endogenous SETD3 in NUDT16-deficient cells did not further exacerbate DNA breaks or enhance the sensitivity of cancer cells to IR treatment." (PMID 38272222, 2024). "Importantly, depletion of endogenous SETD3 in NUDT16-deficient cells does not further exacerbate DNA breaks or enhance the sensitivity of cancer cells to IR treatment." (PMID 38272222, 2024). "The results showed m7G methyltransferases, such as METTL1 and WDR4, were upregulated in a wide range of cancers, while RNA-binding and decapping enzymes (NUDT4, NUDT16, and NUDT10) were significantly downregulated." (PMID 35592316, 2022). "Moreover, ectopic expression of NUDT16 greatly enhanced the resistance of cancer cells to IR treatment; however, depletion of SETD3 in these cells overexpressing NUDT16 largely reversed cell sensitivity towards IR exposure." (PMID 38272222, 2024). "Importantly, depletion of SETD3 in NUDT16-deficient cells did not further exacerbate DNA breaks or enhance the sensitivity of cancer cells to IR exposure, suggesting that the NUDT16-SETD3 pathway may play critical roles in the induction of tolerance to radiotherapy." (PMID 38272222, 2024). "What’s more, the expression of some writer genes (METTL1 and WDR4) and reader genes (AGO2 and NCBP2) was significantly upregulated in most cancers, while the expression of some eraser genes (NUDT12 and NUDT16) and some reader genes (EIF4E3) were downregulated in most cancers." (PMID 36339001, 2022). "When comparing our gene expression analyses and genetic analyses, the cancer genes HLA-DPA1, HLA-DMB, DNAJA4, LY86, HCLS1, GABBR1, NUDT16 showed upregulation in tumor tissue compared to cell subpopulations and are located in chromosomal regions that showed losses in GSC and CD133pos./CD15pos. cells." (PMID 32634135, 2020). "Six of fifty genes were not previously known to associate with cancer (HMGB1L5, LRRC58, GPR149, DZIP1L, C3orf77, and NUDT16)." (PMID 26491211, 2015).
tumor (8 papers, 2020 to 2025). "Collectively, these data suggest that NUDT16 enhances the ability of tumor cells to cope with replication stress by reversing the PARylation and positively regulating the protein expression of HMGA1." (PMID 40288645, 2025). "In the future, we need to further validate the effects of NUDT16-mediated m7G modification on tumor immunosuppression mechanisms in biological experiments such as cell culture and mouse models." (PMID 36389726, 2022). "We found significantly increased infiltration of 23 TME immunocytes in the tumor with low NUDT16 expression compared to those with high expression." (PMID 36389726, 2022). "In addition to NUDT16 being a protective factor, the other three genes (WDR4, EIF4E2, and SNUPN) are risk factors that accelerate tumor progression." (PMID 38987843, 2024). "Therefore, we also speculated that high expression of NUDT16 may suppress tumor immunity by influencing the expression of multiple immune-related cytokines in TME." (PMID 36389726, 2022). "In addition, NUDT16 was brought to our attention in our study because of its remarkable negative association with both tumor prognosis and immunocyte infiltration." (PMID 36389726, 2022). "Only EIF4E3, IFIT5, EIF4G3, NUDT16, NUDT10, NCBP3, and NUDT11 showed decreased expression in tumor tissues." (PMID 41406096, 2025). "Genes such as EIF4E3, IFIT5, EIF4G3, NUDT16, NUDT10, NCBP3, and NUDT11 showed lower expression in tumor tissues, whereas other genes were highly expressed." (PMID 41406096, 2025). "In this study, NUDT16 was also found to be commonly altered and significantly upregulated in CNV among tumor tissues, indicating that it may also promote the development and progression of HCC." (PMID 36389726, 2022).
infection (2 papers, 2022 to 2025). The state of being infected such as from the introduction of a foreign agent such as serum, vaccine, antigenic substance or organism. "Melioidosis patients also exhibited higher NUDT16 expression compared with other causes of severe infection (GSE69528, GSE13015)." (PMID 35174610, 2022). "This analysis revealed that NUDT16 transcript levels increased significantly during the migratory stage of infection (10 h postinfection (hpi), but decreased during the sedentary phase (12 d postinfection (dpi))." (PMID 41165244, 2025). "Using SysInflam HuDB, we found that NUDT16 expression was consistently increased in patients with shock (GSE57065, GSE66099 and GSE95233), and was higher in bacterial infections compared with other types of infections (e.g. viral) (GSE6269, GSE64456 and GSE30119)." (PMID 35174610, 2022).
NUDT16 also shares sentences with these, for which no sentence is quoted: bacterial infections (1 paper); cervical cancer (1); glioma (1); liver fibrosis (1); melanoma (1); nematode infection (1).